CD14 (CD14 molecule)
Diseases named in the same sentence as CD14 in open-access papers (continued):
Sharing a sentence is not in itself a finding about the gene and the disease.
cancer (continued). "The use of BM CD34+ cells from cancer patients also led to the production of up to 60 % CD14+ monocytes containing these subsets, however, occurring at the ratio 1:1." (PMID 23180014, 2013). "Clustering analysis identified a potential biomarker predictive of survival across cancer types consisting of the ratio of CD4+ T cells/μl to CD14+HLA-DRlo/neg monocytes/μL of blood." (PMID 25512872, 2013). "The autologous T lymphocytes isolated from PB of cancer patients were added to CD34+ cell-derived CD14+ monocytes and preexposed to recall antigens, γ-irradiated HPC-4 cells, and TMVHPC." (PMID 23180014, 2013). "Under co-culture conditions the cancer cells express the macrophages-specific antigens, e.g. CD14, CD64, CD163, CSF1R." (PMID 22353646, 2012). "Cells with mesenchymal-like morphology deriving from normal and cancer tissues showed similar levels of CD14, CD29, CD36, CD44, CD45, CD49e, CD73, CDw90, CK18, FLT-1, STRO-1, SH4, HLA-ABC, and integrin α2β1 expression." (PMID 22330345, 2012). "Autologous DCs were generated from 10 patients (HLA-0201) with advanced cancer by culturing CD14+ blood monocytes in the presence of GM-CSF and IL-4 supplemented with TNF-α [DCT] or TNF-α and IFN-α [DCTI]." (PMID 19298672, 2009). "The first aim of our study, therefore, was to compare (using the dual vaccination protocol) specific cytokine combinations (TNF-α +/- IFN-α) to generate activated and functional DCs from circulating CD14+ monocyte precursors in patients with advanced cancer." (PMID 19298672, 2009). "In our previously published work we had shown that this cytokine combination (GM-CSF, IL-4, TNF-α ± IFN-α) was capable of generating DCs in vitro from CD14+ monocytes obtained from healthy individuals and patients with cancer." (PMID 19298672, 2009). "We performed co- immunostainings on controls and on malignant endometrial tissues (G2 carcinoma) with antibodies for CD14 and CD163." (PMID 18775079, 2008). "We further divided cancer cells into six subsets, fibroblasts into six subsets, and immune cells into monocytes (Cd14+ monocytes, M1 macrophages, M2 macrophages, and DCs) and T cells (CD8+ T cells, CD4+ T cells, Dnajb1 high cells, and Dnajb1 low cells)." (PMID 39840525, 2025). "From these clusters, five major cell types were identified via classical cell markers, including T cells (CD3E, CD8A, CD3D), B cells (CD19, MS4A1, CD79A), myeloid cells (CD14, CD68, LYZ), endothelial cells (PECAM1, VWF, CDH5) and cancer-associated fibroblasts (CAFs) (ACTA2, FAP, PDGFRB)." (PMID 39941131, 2025). "Instead, high stiffnesses induced CD14+ populations across all three cancer types." (PMID 39211033, 2024). "Therefore, the here reported increased MERTK expression on CD14+ cDC2s, with the highest expression detected in cancer patients, aligns with the known role of MERTK." (PMID 38242119, 2024). "First, several cancer cell lines were tested for their ability to induce CD14+ cDC2s." (PMID 38242119, 2024). "The 8 cell types were annotated based on the differentially expressed markers: Bnip3 for autophagic cancer cells, Mki67 for proliferating cancer cells, Cd14, Apoe, C1qc, Mrc1, Lyz2 for monocytes, Col3a1 for fibroblasts, Cd3e and Gzma for T cells, Flt1 for endothelial cells, and Klk1 for DCs." (PMID 38802348, 2024). "Collectively, these studies emphasize a role for CD1c+CD14+ cells in cancer." (PMID 38242119, 2024). "Some markers CD14 (monocyte), CD3D (CD4+T cells), CD3E (CD8+T cells), CD68 (macrophage), CST3 (myeloid cells), GNLY (NK cells), KRT18 (epithelial cells), and NKG7 (NK cells) were positively associated with TMSB10 in all cancers." (PMID 37275863, 2023). "Indeed, glucocorticoid induced tolDCs were also seen to elevate the CD8+ Treg (FoxP3+) numbers in the context of cancer and human CD14+ monocytes displayed a similar behavior." (PMID 35784310, 2022).
cancer (continued). "This in vitro model of the cancer TME generates CD14+HLA-DRlo/neg cells with decreased capacity to mature into dendritic cells, elaborate proangiogenic factors, and potently inhibit T-cell proliferation, similar to what is observed with cancer-patient-derived CD14+HLA-DRlo/neg cells." (PMID 36139660, 2022). "CD14+ CD15+ cells have been described previously in cancer patients." (PMID 36189320, 2022). "We found higher median proportions of CD163-positive cells in the cancer group in CD14+16+ (98.08(86.40–100.00)%) and CD14low16+ (99.08(83.47–99.99)%) subsets compared to healthy women: 86.96(77.33–93.02)% for CD14+16+ (p = 0.049) and 60.00 (41.06–91.3)% for CD14low16+ (p = 0.004) cells." (PMID 35237501, 2021). "Thus far, CD14+ cDC2s have been identified only in the context of cancer, but it seems they have important tolerogenic characteristics." (PMID 34445143, 2021). "PD–L1 was recently found to be expressed on CD14+ cells from cancer patients." (PMID 32587357, 2020). "Interestingly, even if patients with advanced-stage cancer, patients with PD–L1+PD–L2+CD14+ cells also have poorer prognosis than similar patients with other types of CD14+ cells." (PMID 32587357, 2020). "PD–L1 is also expressed on CD14+ cells from patients with diverse cancers." (PMID 32587357, 2020). "For flow cytometry based assays, reporting the abundance of CD14+HLA-DRlo/neg monocytes as a percent of PBMCs or total leukocytes is the least informative, particularly when measuring these cells from cancer patients where many patients exhibit severe leukopenia and/or lymphopenia." (PMID 31191529, 2019). "The presence of high levels of CD14+HLA-DRlo/neg monocytes suggests that many of these cancer patients had reached a point of immunoparalysis prior to treatment and thus may not be very responsive to immunotherapeutic approaches." (PMID 31191529, 2019). "However, the fraction of CD14+ and CD14− MDSCs were largely different in pre-RT cancer patients and healthy controls." (PMID 31500214, 2019). "For the first time, our data demonstrated that ARG1 is expressed in human cancer-programmed monocytes, with the suppressive CD14+ monocytes expressing higher amount of the protein and presenting a unique pattern of staining, making them trackable from other circulating monocytes." (PMID 31533831, 2019). "We hypothesize that BDCA1+CD14+ cells are present in a broad spectrum of cancers and demand further investigation to reveal treatment opportunities and/or improvement for DC vaccines." (PMID 30235890, 2018). "Interestingly, we have also observed the relationship of CD14+HLA-DRlo/neg monocytes with granulocytes in cancer patients." (PMID 28742871, 2017). "We have previously shown that the presence of CD14+HLA-DRlo/neg monocytes, where the number of monocytes with low or no expression of HLA-DR was measured as a percentage and as cell counts, is a very good indicator of immune suppression in cancer patients." (PMID 28742871, 2017). "Cells with a CD14+/HLA-DR- phenotype are generally considered to represent monocytic MDSCs when they arise in the presence of cancer cells and have demonstrated immunosuppressive properties, though more stringent characterization as CD11b+ / CD14+ / HLA-DR- / CD15- can also be helpful." (PMID 28666020, 2017). "CD14+ Monocytes (score = 4.88 in the cluster 7 and score = 7.81 in cluster 8) has been reported to affect dendritic cell differentiation and T-cell function in cancer patients." (PMID 29348878, 2017). "Similarly, we tried to induce of cancer antigen-specific CD4+ T cell lines by using CD14-ML-DC derived from cancer patients." (PMID 27050553, 2016). "The products of several genes from our potential cell surface list are suspected of playing key roles in more general cancer-related activities such as immunosuppression/evasion (CD14 and CD86), cell migration (ICAM, CDH11) and proliferation (TGFB1, PMEPA1, PDGFRL, SLC19A3)." (PMID 27363029, 2016).
cancer (continued). "Although we had previously thought that trogocytosis could occur only allogeneically, this finding suggests that autologous transfer of HER2 from cancer cells to CD14+ and CD56+ cells might occur." (PMID 25655677, 2015). "Furthermore, the CD14+HLA-DRlow/− population of monocytes display suppressive properties and have an impact on patient outcomes in various cancers." (PMID 26230952, 2015). "While they found that the increases in the percent of CD14+HLA-DRlo/neg monocytic MDSCs were conserved across the three different processes in cancer patients versus controls, the three processes yielded significantly different monocytic MDSC cell counts (cells/μl)." (PMID 25799053, 2015). "Knowing that CD14+HLA-DRlo/neg monocytes have significant capacity to influence ex vivo DC cultures implies that these cells and the pathways to both generate and eliminate them are high-value targets to improve cancer therapies." (PMID 24772111, 2014). "Moreover, the percentage of CD11b+CD14+HLA-DR− cells was significantly elevated in the cancer patients (17.3±6.4%) relative to the healthy donors (2.4±1.48%)." (PMID 25238263, 2014). "However, CD11b+MHCII− cells that were purified from dogs with advanced cancer that were also CD14+ potently inhibited T cell proliferation, revealing that although monocytic MDSC are not a dominant population in dogs with cancer, they are indeed present." (PMID 22428007, 2012). "However, CD14 plays a controversial role in cancer regulation." (PMID 40092684, 2025). "Interestingly, several previous studies demonstrated the negative correlation between CD14-positive immune cells associated with tumors and survival prognosis in cancer patients." (PMID 39684692, 2024). "Higher levels of CD163, CD14, Fibronectin, B7-H3, LAG3, Tim-3, PD-L1, VISTA, CD25, and CD44 associated with fibroblasts, myeloid-derived cells, T cells, and NK cells were found in the ‘surrounding stromal leukocytes’ cf. ‘immune-rich cancer cell islet’ regions." (PMID 37046826, 2023). "However, in our model system, cancer cell outgrowth was related to the cross-talk with CD14+ cells." (PMID 36139660, 2022). "Therefore, the blockade of TIM-3 on CD14+CD68+CD163+ macrophages might improve cancer immunosuppression." (PMID 36293034, 2022). "Notably, human CD1c (BDCA-1)+ myDCs are heterogeneous, with a CD14-positive subpopulation that is immunosuppressive and a CD14-negative subpopulation that is capable of mediating antitumor immune responses induced by immunogenic cancer cell death." (PMID 33182610, 2020). "However, few studies exist on PD–L2 expression by CD14+ cells from patients with diverse cancers." (PMID 32587357, 2020). "Thus, it would be very useful if CD14-ML could be established not only from healthy donors but also from cancer patients." (PMID 27050553, 2016). "As this subset may have a very low or even no HLA-DR expression, it can also be found as CD14+/HLA-DR−/lo monocytes in the literature and has already been associated with cancer prognosis." (PMID 27529227, 2016). "CD14+/CD16+ monocytes, coexpressing CD16 and low levels of CD14, were first characterized by Ziegler-Heitbrock and colleagues in 1988, and their number and phenotype/function have been reported to be altered in patients with cancer, infectious diseases or inflammatory disorders." (PMID 21586124, 2011). "In experiments comparing CD14-high and CD14-low MB49 cancer cells generated through serial FACS sorting and passaging, CD14-high cells exhibited greater enrichment of neutrophil-recruiting chemokines, such as CXCL1 and CXCL2, than did CD14-low cells." (PMID 41486114, 2026). "As expected, EMD-CMs from PShigh cells induced robust THP-1 differentiation based on CD14 expression compared to PSlow cells such as primary human astrocytes, primary human pancreatic duct epithelial (HPDE) cells, and AsPC-1 cancer cells." (PMID 40227806, 2025).
cancer (continued). "For example, the proportion of CD3+CD8+ cytotoxic T cells was higher in T1 than in T2 cancer, and the percentage of CD11b+CD14−/CD33+CD14− PMN-MDSCs was lower in T1 than in T2 cancer." (PMID 41051525, 2025). "As it can be inferred, THCs are identified by the expression of hematopoietic markers, including CD14, CD45 and CD163, provided by the myeloid partner, as well as common cancer-related markers (e.g. cytokeratin or EpCAM)." (PMID 39967663, 2025). "Lidocaine increased the production of the anti-cancer-related cytokines IFN-γ by sorted CD8+ TIICs and IL-12 by sorted CD14+ TIICs." (PMID 40244064, 2025). "Regulation and production of the anti-cancer-related cytokines IFN-γ in CD8+ TIICs and IL-12 in CD14+ TIICs by lidocaine were analyzed." (PMID 40244064, 2025). "Using the deconvolved TCGA-BRCA dataset, we found that patients with high CD200 levels in cancer cells also showed high levels of CD200R1 in NK cells, CD14+ myeloid cells, and Treg, consistent with our observations in mouse models." (PMID 40568095, 2025). "These cells are predominantly of CD14+CD16- phenotype (intermediate monocytes), losing their anti-cancer activity and suppressing other immune cells." (PMID 40136652, 2025). "Bioinformatical analysis helped us to reveal distinct cancer-specific features in CD14.Mn.S100A8.9hi, CD14.Mn.MHC2hi and CD16.Mn subsets." (PMID 39315092, 2024). "We examined the percentages of CD3+, CD3+CD4+, CD3+CD8+, CD14+, and CD3-CD16+CD56+ cells in PBMC samples from 520 cancer patients and 109 healthy individuals, as well as the factors that affected them." (PMID 38911366, 2024). "Cancer patients had a lower proportion of CD3+ cells than healthy individuals (45.54%/55.83%, P <0.0001), but a higher proportion of CD14+/CD3-CD56+CD16+ cells (30.04%/15.17%, P <0.0001 versus 17.45%/14.93%, P =0.0037)." (PMID 38911366, 2024). "To further evaluate the relative contribution of the myeloid cells to the cancer cell-killing activity in PBMC co-cultures, we depleted the CD14+ monocytes from PBMCs, which retained the CD3+ lymphocytes." (PMID 38992037, 2024). "Through this analysis, we identified eight major cell types, namely B cell (CD79A), cancer cell (KRT5), cycling cell (MKI67), endothelial cell (VWF), fibroblast (COL1A1), mast cell (KIT), monocyte/macrophage (CD14) and T cell (CD3D)." (PMID 38279519, 2024). "In patients with RCC as well as with other cancers, granulocytic (G) MDSCs (CD33+, HLADR−, CD15+, CD14− dominate over monocytic (M) MDSCs (CD33+, HLADR−, CD15−, CD14+), as seen in mouse models." (PMID 36614308, 2023). "Analysis of the CRC dataset from the cancer genome atlas (TCGA) demonstrated a positive correlation between THBS1 and mesenchyme-related genes (VIM and FN1) and pan-myeloid markers (CD14 and CD33)." (PMID 37749092, 2023). "Recent studies have shown that CD33+CD11b+HLA-DR–/lo cells from cancer patients have a complete overlap with monocytic-MDSCs and PMN-MDSCs, which were often defined as cells co-expressing CD14 and CD1537,38." (PMID 36878933, 2023). "We uncovered a Hippo regulon in neutrophils with unique YAP signature genes (e.g., ICAM1, CD14, EGR1) distinct from those identified in epithelial and/or cancer cells." (PMID 36921037, 2023). "It has been suggested to regulate the crosstalk between inflammation and autophagy by evoking a switch between pro-inflammatory CD14 and pro-autophagic CD44 co-receptors for TLRs relevant to cancer progression." (PMID 35267503, 2022). "Several publications in the literature showed that CD14+ monocytes in mobilized peripheral stem cells (PSC) and PBMC isolated from cancer patients inhibited T-cell activation." (PMID 36536403, 2022). "Epithelial cell adhesion molecule (EpCAM)+ cancer cells (PD-L1− or T cell immunoglobulin mucin-3, TIM-3−), both PD-1 or TIM-3 positive CD8+ T cells, and CD14+CD68+CD163+TIM-3+ macrophages increased from the MPE1st to MPE2nd." (PMID 36293034, 2022).
cancer (continued). "In patients who developed cancer recurrence and had low SMA on staging CT TAP, significantly higher systemic levels of CRP, IL-6, VEGF, and expression of cell surface receptor CD14 were observed." (PMID 34459908, 2021). "In contrast, the top impacted pathways in response to DEX treatment in blood CD14+ monocytes were as following; cytokine-cytokine receptor interaction (FDR = 6 × 10−6) and transcriptional misregulation in cancer (FDR = 1 × 10−4)." (PMID 32477331, 2020). "We have also previously shown that MBZ induces an M1 phenotype in human macrophage models and potentiates the anti-cancer activity of CD3/IL-2 activated peripheral blood mononuclear cells (PBMCs), the effect being attenuated by removal of CD14+ myeloid cells." (PMID 32753665, 2020). "CD14+ cells were isolated from 15 naïve early-stage HCC patients before treatment initiation and after cancer progression to advanced stages." (PMID 32824016, 2020). "The PanTum Detect test is a novel screening test based on two general markers in cancer, Apo10 and TKTL1, which can be detected with intracellular staining and FACS analysis in CD14+CD16+ gated circulating monocytes using EDIM technology." (PMID 32438648, 2020). "Recently, several studies have described relationships among TLRs, CD14, CD25, CD28, and CD61 and the evolution of human cancers." (PMID 31523179, 2019). "A similar pattern of restricted expression is also observed for the other antisense TSSs: PRKN-int3AS and PRKN-int4AS in cancer cell lines, PARKN-int5AS in ARPE-19 EMT cells induced with TGFβ and TNFα, and PARKN-3′AS1 in CD14+ monocytes." (PMID 30610612, 2019). "Specifically, CD45+/CD14−/2NBDG−, CD45+/CD14+/2NBDG+, and CD45−/CD14−/2NBDG+ events are ascribed to lymphocytes, monocytes (macrophages and dendritic cells), and cancer cells (A549), respectively." (PMID 30109276, 2018). "Following five days of incubation, the surface CD14 expression was determined, and it was found that PAO and CD45i reversed cancer cell-mediated TADC differentiation in the IL-10, A549, MDA and SW480 groups." (PMID 25013476, 2014). "Most of these cell lines were derived from lymphocytes from normal blood (e.g., T cells CD4+ Th0 adult, Monocytes CD14+ RO01746), while some cell lines came from cancer patients (e.g., Gliobla and HeLa-S3)." (PMID 25393678, 2014). "The total population of monocytes (CD14+ cells), used at different doses, exhibited substantial spontaneous cytotoxicity towards HPC-4 and DeTa cancer cells." (PMID 23180014, 2013). "The percentages of mouse CD31, CD90, CD49b, CD14 and CD11c positive cells in the subpopulation of the cancer cells were almost below the detection level (0.9%: CD31; 0.4%: CD90; 1.6%: CD49b; 1.7%: CD14 and 0.4%: CD11c." (PMID 22672897, 2012). "Our confocal imaging and IHC examination has proven that under co-culture conditions expression of macrophages markers (CD14, CD64, CSF1R) in almost all of the cancer cells was initiated." (PMID 22353646, 2012). "We compared the expression of S15 on CD19+ B cells, CD3+ T cells and CD14+ monocyte cell populations within human PBMCs relative to H460 NSCLC and Panc-1 PDAC cancer cells, and found detectable but markedly lower S15 expression relative to the cancer cells." (PMID 40365291, 2025). "In LYM, CD14+ monocytes, CD16+ monocytes, cDC2, and pDCs had high polarization scores of all polarization states, supporting the strong effect and important role of multiple cytokines in the cancer." (PMID 39999031, 2025). "The result showed that the difference in distribution of CD14+ cells and CD19+ cells may be one of the factors contributing to the different survival outcomes in pan-cancer." (PMID 40004489, 2025). "Jurkat cells expressing the MC.27.759S TCR responded to multiple cancer cell lines that naturally expressed either MR1*01 or MR1*02 but did not respond toward healthy CD14+ monocytes or CD19+ B cells from 3 donors." (PMID 39744940, 2025).